CFTR (CF transmembrane conductance regulator)
Diseases named in the same sentence as CFTR in open-access papers (continued):
Sharing a sentence is not in itself a finding about the gene and the disease.
cystic fibrosis (continued). "Cystic Fibrosis affects various organs in which the CFTR protein is normally expressed." (PMID 24688726, 2013). "Consistently, in the airway epithelial cells, a high level of GSH delivery to the extracellular space was greatly diminished in cells derived from ΔF508 homozygous cystic fibrosis patients and could be restored by repleting the cells with normal CFTR protein." (PMID 23383255, 2013). "Reduced expression of CFTR is also characteristic of many cell type in cystic fibrosis." (PMID 23358229, 2013). "Microarray studies related to cystic fibrosis airway gene expression have gone some way in clarifying the complex molecular background of CF lung diseases, but have made little progress in defining a robust “molecular signature” associated with mutant CFTR expression." (PMID 23537407, 2013). "Moreover, previous studies revealed that the commonest cystic fibrosis mutation F508del, which prevents the plasma membrane expression of CFTR, slowed MDCK cyst enlargement by inhibiting CFTR-mediated fluid accumulation within the cyst lumen." (PMID 23536832, 2013). "With a view to developing a cell-based therapy for cystic fibrosis we have shown that human amnion epithelial cells (hAECs) can be induced to express functional cystic fibrosis transmembrane conductance regulator (CFTR) in vitro by culture in media designed for lung cell differentiation." (PMID 23029546, 2012). "Finally, modulation of the specific function of a mutated protein can be obtained, as has recently been documented in a successful clinical trial of CFTR conductance modulators for cystic fibrosis." (PMID 22704758, 2012). "Alternatively, if the interest is primarily in cystic fibrosis, a knockout mice model of cystic fibrosis transmembrane conductance regulator (CFTR) may be used." (PMID 23201848, 2012). "Cystic fibrosis is a lethal genetic disease caused by lack of functional cystic fibrosis transmembrane conductance regulator (CFTR) proteins at the apical surface of secretory epithelia." (PMID 22973227, 2012). "Moreover, these positions were implicated in cystic fibrosis-related folding defects of NBD1, in the correction of these defects and in CFTR channel gating." (PMID 22590562, 2012). "For example, the diagnostic accuracy of a new genomic assay to measure cystic fibrosis transmembrane conductance regulator (CFTR) genotype would be compared with a functional assay, such as the sweat test, which is still the current standard for diagnosing cystic fibrosis." (PMID 23078403, 2012). "The significance of this gene group is evident in the fact that polymorphisms in the cystic fibrosis transmembrane conductance regulator (CFTR) gene, a chloride transporter, result in cystic fibrosis, a lethal hereditary disorder with a dramatic pulmonary phenotype." (PMID 22375630, 2012). "School of Medicine for polyclonal anti-CFTR antibody, R. J. Bridges (Rosalind Franklin University of Medicine and Science) and the Cystic Fibrosis Foundation Therapeutics (CFFT) for VRT-325, and E. Ficker (Case Western Reserve University, Cleveland, OH, USA) for providing the HERG constructs." (PMID 22988441, 2012). "The DNA sequencing analysis showed there were no mutations induced by WGA in this approximately 2 kb region of the CFTR gene (mutation induction was less than 4 x 10-5), which indicates that WGA DNAs can be used for enrichment of DNA samples for cystic fibrosis genotyping assays." (PMID 22655855, 2012). "Cystic fibrosis (CF, OMIM#219700) is an autosomal recessive monogenic disease, caused by two defective copies of the cystic fibrosis transmembrane conductance regulator (CFTR) gene." (PMID 21548936, 2011). "The protection of ductal cells depends on maintaining an alkaline pH and a rapid enzyme flow into the duodenum, which requires normal functioning of CFTR (cystic fibrosis transmembrane conductance regulator or transmembrane conductance regulator Cystic Fibrosis)." (PMID 21845156, 2011).
cystic fibrosis (continued). "In addition, the only known transporter that places GSH in the ELF is CFTR, the gene defective in cystic fibrosis." (PMID 21982222, 2011). "Especially encouraging recent reports indicated that enhancement from 1% to only 5% of normal CFTR levels may greatly reduce the severity or eliminate principal manifestations of cystic fibrosis." (PMID 21695138, 2011). "Our observations indicate that activators of ANO1, which may be useful in other pathological settings (e.g., compensation for the inactive CFTR chloride channel in cystic fibrosis), could potentially have undesirable effects on tumours through ANO1." (PMID 20664600, 2010). "The CFTR amino acid sequence contained 12 domains previously recognized as membrane-spanning sequences, and in vitro gene transfer experiments demonstrated restoration of chloride channel function in cystic fibrosis pancreatic cells." (PMID 21994643, 2010). "Mainstream cigarette smoke inhibited both CFTR expression and function both in vitro in immortalized cell lines and in vivo where nasal potential difference measurements were consistent with inhibition of Cl- transport similar to that seen in cystic fibrosis." (PMID 19943936, 2009). "Each ENaC subunit activity may be regulated by other proteins such as CFTR (Cystic Fibrosis Transmembrane conductance Regulator) which is the protein involved in cystic fibrosis." (PMID 18507830, 2008). "This marker is associated with the gene CFTR (cystic fibrosis transmembrane conductance regulator; MIM:*602421), which has been well studied as mutations in it cause the autosomal recessive disorder cystic fibrosis." (PMID 16904005, 2006). "Thus, cDNA for the human CFTR gene, the therapeutic gene for cystic fibrosis, has one hotspot consensus sequence and cDNA for the human dystrophin gene, the therapeutic gene for DMD, has three such potential hotspots." (PMID 16529656, 2006). "Despite cystic fibrosis transmembrane conductance regulator (CFTR) proteins being present throughout the entire body and organ systems, typical presentation of cystic fibrosis involves lung disease." (PMID 41536752, 2026). "However, the contribution of common CFTR polymorphisms, such as T5 or TG12, and bicarbonate-defective CFTR variants that do not cause cystic fibrosis remains a subject of ongoing debate, as most evidence to date does not strongly link them with CP." (PMID 41510163, 2026). "CF patients were examined at baseline and after 12-18 months of cystic fibrosis transmembrane conductance regulator (CFTR) modulator therapy." (PMID 42279171, 2026). "Cystic Fibrosis Transmembrane Conductance Regulator (CFTR) dysfunction is increasingly recognized as a key contributor to a broad spectrum of human diseases beyond classical cystic fibrosis." (PMID 42274626, 2026). "Intriguingly, evidence from patients with CF suggests that neutrophils display a pro-survival cystic fibrosis transmembrane regulator (CFTR)-dependent phenotype, which prolongs their presence in the airways and induces NETs production." (PMID 40589741, 2025). "Advances in cystic fibrosis therapy over the last decade have substantially improved lung function and reduced pulmonary exacerbations, particularly for people with CF (pwCF) treated with highly effective cystic fibrosis transmembrane conductance regulator (CFTR) modulator therapy (HEMT)." (PMID 41198444, 2025). "Cystic fibrosis is an autosomal recessive condition resulting from a three‐base‐pair deletion (F508del) in the CFTR gene." (PMID 40014809, 2025). "Cystic fibrosis transmembrane regulator (CFTR)–directed therapies, such as modulators, have transformed the medical management of people with CF, resulting in better lung function, weight, and body mass index in recent years." (PMID 40533897, 2025). "Cystic fibrosis transmembrane conductance regulator (CFTR) modulators have been reported to improve lung function and reduce CF exacerbations." (PMID 41465734, 2025).
cystic fibrosis (continued). "In cystic fibrosis, the defect of the CF transmembrane conductance regulator (CFTR) can also affect sensory nerve cell function, as recently demonstrated in animal models." (PMID 41347296, 2025). "A well-studied example is cystic fibrosis transmembrane conductance regulator (CFTR) gene mutations, which can cause cystic fibrosis depending on the levels of transforming growth factor (TGF)-β1." (PMID 40533538, 2025). "Newborn screening (NBS) programs have elucidated the true incidence of CF in a variety of populations and enabled rapid genotype identification through the analysis of the cystic fibrosis transmembrane regulator (CFTR) gene." (PMID 40265448, 2025). "Although incomplete, the partial recovery of CFTR function has been shown to drastically lower sputum pathogen content, enhance microbiome diversity, and lower inflammation markers within the first year of treatment in adolescents and adults with cystic fibrosis." (PMID 40227282, 2025). "Cystic fibrosis (CF; MIM: 219700) is a hereditary disorder transmitted in an autosomal recessive pattern, resulting from mutations in the gene encoding the CFTR (cystic fibrosis transmembrane conductance regulator) protein." (PMID 40943949, 2025). "Cystic fibrosis transmembrane conductance regulator (CFTR) triple modulator therapy, elexacaftor–tezacaftor–ivacaftor (ETI) has transformed care for people with cystic fibrosis who have eligible mutations." (PMID 40013020, 2025). "The development of CFTR modulators has revolutionized cystic fibrosis therapy, providing effective treatments for the majority of people with CF." (PMID 39996840, 2025). "CF results from sequences changes in the CFTR (cystic fibrosis transmembrane conductance regulator) gene, located on chromosome 7." (PMID 41209022, 2025). "Intriguingly, recent studies have demonstrated that seemingly healthy individuals in the general population who carry one normally functioning and one compromised copy of the CFTR gene may exhibit related yet less severe symptoms typical of cystic fibrosis as well." (PMID 39825393, 2025). "CF is a monogenic, chronic, and multisystemic condition resulting from pathogenic mutations in the CFTR (cystic fibrosis transmembrane conductance regulator) gene, located on the long arm of chromosome 7 (7q31)." (PMID 41010996, 2025). "The emergence of cystic fibrosis transmembrane conductance regulator (CFTR) modulator drugs has revolutionized CF care, but reactions to these medications have been reported." (PMID 40933958, 2025). "A landmark application is in cystic fibrosis, where rectal PDOs predicted better the individual responses to CFTR modulators, marking the first clinical use of organoids to guide therapy." (PMID 41278202, 2025). "Ionocytes express elevated levels of transcripts encoding the cystic fibrosis transmembrane conductance regulator (CFTR) protein, an anion channel defective in patients with cystic fibrosis." (PMID 41303221, 2025). "Cystic fibrosis was once a fatal disease of childhood, but with advances in combination CFTR modulator therapies, life expectancy for persons with CF (PwCF) has increased." (PMID 40778643, 2025). "These variants can manifest as a spectrum of conditions, from asymptomatic to cystic fibrosis and CFTR-related disorders (CFTR-RDs), such as CBAVD." (PMID 40169970, 2025). "Cystic fibrosis is a genetic disorder stemming from dysfunction in the CF Transmembrane Conductance Regulator (CFTR)." (PMID 40969560, 2025). "Caused by mutations in the cystic fibrosis transmembrane conductance regulator (CFTR) gene, CF leads to the production of thick and sticky mucus, which can clog airways, trap bacteria, and cause persistent lung infections." (PMID 40282362, 2025). "In cystic fibrosis, CF transmembrane regulator (CFTR), an ATP binding cassette, is required for HCO3− secretion, and a mutation in CFTR leads to a defect in this anion in the CF lung." (PMID 40047280, 2025).
cystic fibrosis (continued). "CF is an autosomal recessive disease due to variations in the cystic fibrosis transmembrane conductance regulator (CFTR), affecting the respiratory and GI tract and impacting metabolism and fertility in males." (PMID 41156789, 2025). "This vital process is hindered in chronic inflammatory respiratory diseases, such as chronic obstructive pulmonary disease (COPD), asthma, cystic fibrosis [in which CF transmembrane conductance regulator (CFTR) is impaired], or respiratory infections." (PMID 40590703, 2025). "Cystic fibrosis (ORPHA: 586; OMIM: 219700) is a rare autosomal recessive genetic disease caused by mutations in the cystic fibrosis transmembrane conductance regulator (CFTR) gene located on chromosome 7q31.2 (OMIM, 602421)." (PMID 40806984, 2025). "Here we describe the systematic optimization of PE systems to efficiently correct human cystic fibrosis transmembrane conductance regulator (CFTR) F508del, a three-nucleotide deletion that is the predominant cause of CF." (PMID 38987629, 2025). "The absence of negative effects of carriage of pathogenic CFTR variants on male fertility indicators could contribute to their widespread distribution and the persistent prevalence of cystic fibrosis and infertility within the general population." (PMID 40724872, 2025). "The advent of cystic fibrosis transmembrane conductance regulator (CFTR) modulators has revolutionized the management of cystic fibrosis." (PMID 41246920, 2025). "Cystic fibrosis is a disease affecting the chloride transmembrane transport channel—cystic fibrosis transmembrane conductance regulator (CFTR), present in the epithelial cells of many vital organs." (PMID 40149535, 2025). "CF is a genetic condition that results in the absence or dysfunction of a specific anion channel (CFTR: the cystic fibrosis transmembrane conductance regulator) on epithelial surfaces including the airway epithelium." (PMID 41237141, 2025). "Another example of the application of organoids are the treatment of cystic fibrosis, a genetic disorder caused by mutations in the CFTR (CF transmembrane conductance regulator) gene." (PMID 40932932, 2025). "The licensing of cystic fibrosis transmembrane conductance regulator (CFTR) modulator drugs has led to reduced pulmonary exacerbations, morbidity, and increased survival in those with CF." (PMID 40698812, 2025). "This review explores how nutritional status is evolving in the era of cystic fibrosis transmembrane conductance regulator (CFTR) modulators in people with CF, specifically in children." (PMID 40806116, 2025). "CFTR mutation analysis should be reserved for cases without renal anomalies or for those presenting with bilateral vasal agenesis, especially in regions with a low prevalence of cystic fibrosis." (PMID 41306546, 2025). "This synergybetween cutting-edge deep learning approaches not only acceleratesfundamental discoveries in CFTR research but also holds immense potentialfor therapeutic advancements, ultimately contributing to the developmentof precision medicine strategies for cystic fibrosis treatment." (PMID 41358137, 2025). "Wide‐spread use of cystic fibrosis transmembrane conductance regulator (CFTR) modulators has resulted in a dramatic increase in life expectancy of people with CF." (PMID 41147257, 2025). "Additionally, in cystic fibrosis research, patient-derived intestinal and airway organoids were successfully employed to evaluate the modulator efficacy of the CF transmembrane conductance regulator (CFTR) and optimize personalized treatment strategies." (PMID 41359105, 2025). "Recently, cystic fibrosis transmembrane conductance regulator (CFTR) modulators have provided effective treatment for CF patients, extending life expectancy and reducing morbidity." (PMID 41209289, 2025). "Among such genes is CFTR, responsible for cystic fibrosis —an autosomal recessive disorder characterised by chronic pulmonary infections and intestinal malabsorption." (PMID 40861057, 2025).
cystic fibrosis (continued). "While the precise role of rs4727853 remains unclear, the established link between CFTR dysfunction and inflammation in cystic fibrosis and autoimmune pancreatitis suggests a potential connection to GM, a disease with possible autoimmune features supported by the presence of T-cells." (PMID 39796280, 2025). "Modulator therapy restores CFTR function and has led to health benefits for persons with cystic fibrosis (PwCF), including lower rates of pulmonary exacerbations." (PMID 40918666, 2025). "With the advent of modulator therapy, there have been many reports of people with cystic fibrosis stopping their inhaled antibiotics, with a recent paper describing the need for updated guidance for the management of infection in people who use CFTR modulators." (PMID 39861758, 2025). "This is a 14-year-old male patient with CF before the approval of triple cystic fibrosis transmembrane conductance regulator (CFTR)-modulator therapy." (PMID 40151183, 2025). "Intestinal current measurement (ICM) provides a sensitive bioassay for assessment of cystic fibrosis transmembrane conductance regulator (CFTR) function in rectal biopsies ex vivo and is used as a diagnostic tool for cystic fibrosis." (PMID 40066329, 2025). "Additionally, the ability of cR11A to target ionocytes after intravenous injection has profound implications for cystic fibrosis due to these cells having a high expression of CFTR protein, and their ability to mediate chloride absorption across the airway epithelium." (PMID 40733033, 2025). "The cystic fibrosis transmembrane conductance regulator (CFTR) gene, errors in which cause CF, is expressed in ductal epithelial cells at many sites." (PMID 40785146, 2025). "Cystic fibrosis is a life-limiting autosomal recessive disease often treated with triple CFTR modulator therapy (elexacaftor/tezacaftor/ivacaftor, ETI)." (PMID 40986223, 2025). "We assessed the efficacy and safety of vanzacaftor–tezacaftor–deutivacaftor, a novel, once-daily CFTR modulator, compared with elexacaftor–tezacaftor–ivacaftor (standard of care for eligible people with cystic fibrosis) in 971 adolescents and adults with cystic fibrosis with diverse genotypes." (PMID 39756424, 2025). "CF is an autosomal recessive disorder characterized by a defect in cystic fibrosis transmembrane conductance regulator (CFTR) that regulates chloride and bicarbonate secretion across the pulmonary epithelium." (PMID 40415956, 2025). "In recent years, there has been significant progress made in CF treatment and outcomes with the advent of cystic fibrosis transmembrane conductance regulator (CFTR) modulators." (PMID 39210645, 2024). "Cystic fibrosis is a genetic disorder that disrupts CF transmembrane conductance regulator (CFTR) anion channels and impairs airway host defenses." (PMID 38888974, 2024). "Interestingly, EMC members were required to enhance biogenesis of a mutant CFTR channel in yeast, and could therefore modulate cystic fibrosis severity." (PMID 39456191, 2024). "We then compare the airway surface liquidpH measured using SERS-MS in ALIs grown from Cystic Fibrosis and non-CysticFibrosis human donors to explore whether CFTR mutations result inabnormal pH regulation." (PMID 38659220, 2024). "This is exemplified by the most frequent CFTR pathogenic variant NM_000492.3:c.1521_1523del; p.(Phe508del) in cystic fibrosis (MAF~0.015 in Non-Finnish Europeans) and the GJB2 variant NM_004004.5:c.35del; p.(Gly12ValfsTer2) in non-syndromic sensorineural deafness (MAF~0.01 in Non-Finnish Europeans)." (PMID 39201349, 2024). "The landscape of cystic fibrosis is changing, as the highly effective CF transmembrane conductance regulator (CFTR) modulating drug, elexacaftor–tezacaftor–ivacaftor (ETI), is now available for people with CF (pwCF) with at least 1 F508del mutation." (PMID 38935410, 2024).